TMEM89 (transmembrane protein 89)
Tractability: Antibody: UniProt predicts a signal peptide or a membrane-spanning region.
Gene: Protein-coding gene on chromosome 3 (48,620,759 to 48,621,769, reverse strand). Ensembl gene ENSG00000183396.
Subcellular location: Membrane
Subcellular location (Human Protein Atlas): Perinuclear theca
Gene Ontology:
Molecular function: protein binding
Cellular component: nucleus; membrane
Genetic constraint (gnomAD): Loss-of-function variants: 7 observed, 11.36 expected, observed/expected ratio (o/e) 0.62, 90% interval 0.35 to 1.16. The upper end of that interval is the gene's LOEUF score, 1.16, which puts it in group 5 of 6, group 1 being the genes least tolerant of losing a copy. Missense variants: 220 observed, 225.64 expected, observed/expected ratio (o/e) 0.98, 90% interval 0.87 to 1.09. Synonymous variants: 96 observed, 96.58 expected, observed/expected ratio (o/e) 0.99, 90% interval 0.84 to 1.18.
Homologues: Orthologues: chimpanzee TMEM89 (99% identical), macaque TMEM89 (95% identical), pig TMEM89 (69% identical), rabbit TMEM89 (64% identical), dog TMEM89 (62% identical), rat Tmem89 (59% identical), guinea pig TMEM89 (57% identical), mouse Tmem89 (57% identical).